MMP3 (matrix metallopeptidase 3)
Diseases named in the same sentence as MMP3 in open-access papers (continued):
Sharing a sentence is not in itself a finding about the gene and the disease.
osteoarthritis (continued). "Similarly, MMP-13, MMP-3, MMP-2, and MMP-9 increased in the cell line model of osteoarthritis." (PMID 32189997, 2020). "In our study, catabolic genes, including MMP-3 and -9 and ADAMTS5, and the proinflammatory cytokines, including CCL-2 and-5 and CXCL1, were also inhibited by DHA treatment, suggesting the potential role of DHA in maintaining cellular homeostasis and treating osteoarthritis." (PMID 27941926, 2016). "MMP3 is involved in the remodeling and turnover of the ECM, therefore playing an important role in angiogenesis, wound healing, embryogenesis and morphogenesis and contributing to pathological processes such as cancers, myocardial infarction, fibrotic disorders, rheumatism and osteoarthritis." (PMID 23967200, 2013). "However, the role of naringenin in modulation of MMP-3 in osteoarthritis has not yet been explored." (PMID 28355351, 2017). "A genome-wide analysis of DNA methylation status involving osteoarthritis patients found the MMP3, MMP9, and MMP13 genes to be hypomethylated (with increased gene expression) in osteoarthritis versus non-osteoarthritis chondrocytes." (PMID 33920915, 2021). "From this point of view, we emphasized the positive and negative roles of MMP-3 in the pathogenesis of disease and cell differentiation, highlighting that MMP-3 is especially closely involved in the occurrence and development of osteoarthritis." (PMID 34276395, 2021).
rheumatoid arthritis (143 papers, 2005 to 2026). A chronic, systemic autoimmune disorder characterized by inflammation in the synovial membranes and articular surfaces. "In inflammatory diseases involving bone and cartilage, such as rheumatoid arthritis (RA), ankylosing spondylitis (AS), and OA, the generally high level of serum MMP-3 suggests its potential as a diagnostic marker." (PMID 34276395, 2021). "Although the correlation between ox-LDL, LOX-1 and MMP3 is implicated in rheumatoid arthritis (RA) and OA21, 25, its role in the pathophysiology of IVDD remains unknown." (PMID 28785062, 2017). "As a key enzyme in the cartilage degeneration associated with OA and rheumatoid arthritis (RA), MMP-3 activity correlates positively with the severity of articular cartilage damage, making it a biomarker for disease progression." (PMID 41458513, 2025). "AP-1 transcriptionally orchestrates cartilage-degrading matrix metalloproteinases (MMP1/MMP3) in the pathogenesis of rheumatoid arthritis." (PMID 40647090, 2025). "MMP-3 is a proteinase produced by synovial cells and chondrocytes in the joint and is used as a biomarker for joint destruction in patients with rheumatoid arthritis." (PMID 39838480, 2025). "In particular, MMP-3 is a reliable marker of rheumatoid arthritis disease activity, imaging monitoring, prognosis, and response to treatment." (PMID 37996918, 2023). "Studies have reported that there is a positive correlation between disease and MMP3 expression, and the severity of rheumatoid arthritis will change with changes in serum MMP3 expression." (PMID 36670802, 2023). "MMP3 is a protease that is synthesized and secreted by synovial fibroblasts and chondrocytes, and it can be used as a reliable marker of rheumatoid arthritis." (PMID 36544491, 2022). "MMP3, also known as stromelysin-1, is a proteinase synthesized and secreted by synovial fibroblasts and chondrocytes in the joints; it is actively involved in joint destruction in rheumatoid arthritis patients." (PMID 35571618, 2022). "In rheumatoid arthritis (RA), MMP3 has also been suggested to cleave m-CD95L and accumulate s-CD95L in the synovial fluid of these patients." (PMID 36544756, 2022). "Resveratrol shows its anti-rheumatoid arthritis properties with reduced RA patients’ swelling, tenderness, and disease activity by lowering the biochemical indicators of inflammation like MMP-3, IL-6, ESR, C-reactive protein, and undercarboxylated osteocalcin." (PMID 35237163, 2022). "RasGRF1 was significantly enhanced in rheumatoid arthritis synovial tissue, and it contributed to Matrix metalloproteinase-3 (MMP-3) production." (PMID 35740904, 2022). "Another study showed that the expression of serum CTX-II was significantly increased and positively correlated with MMP3 in rheumatoid arthritis, deeming it as a vital indicator to judge the severity and prognosis of rheumatoid arthritis." (PMID 34395611, 2021). "TNF-α significantly induced IL-33 mRNA expression and protein synthesis, and overexpression of IL-33 significantly increased TNF-α-induced IL-6, IL-8, and matrix metalloprotease (MMP)-3 in rheumatoid arthritis synovial fibroblast." (PMID 33490289, 2020). "In this study, we show that CBD increases intracellular calcium levels, reduces cell viability and IL-6/IL-8/MMP-3 production of rheumatoid arthritis synovial fibroblasts (RASF)." (PMID 32873774, 2020). "Ginkgetin reduced arthritic inflammation in rat adjuvant-induced arthritis, while resveratrol showed inhibitory effects on TNF-α-induced IL-1β and MMP-3 production in human rheumatoid arthritis fibroblast-like synoviocytes." (PMID 31757048, 2019). "To date, resveratrol (stilbenes grape) also inhibits TNF-alpha-induced MMP-3 production in human rheumatoid arthritis fibroblast-like synoviocytes via a modulation of the PI3kinase/Akt pathway." (PMID 31888255, 2019).
rheumatoid arthritis (continued). "MMP-3 was significantly reduced by the addition of adalimumab therapy in patients with rheumatoid arthritis and by TNF-α antagonist therapy (infliximab, etanercept, and adalimumab) in patients with spondyloarthritis." (PMID 31686457, 2019). "The aim of this study was to clarify whether serum matrix metalloproteinase 3 (MMP-3) levels are associated with an effect of iguratimod as add-on therapy to biological DMARDs (bDMARDs) in patients with rheumatoid arthritis (RA)." (PMID 30138480, 2018). "MMP-3 and M-CSF need further testing to determine their performance in differentiating PsA from rheumatoid arthritis (RA) and inflammatory osteoarthritis of the interphalangeal joints." (PMID 28934972, 2017). "This study aimed to investigate the reliability and validity of serum matrix metalloproteinase-3 (MMP-3) levels and articular ultrasound (US) scores in assessing disease activity and therapeutic response in rheumatoid arthritis (RA) patients." (PMID 29141665, 2017). "Here, we tested the role T-614 on the IL-6-induced receptor activator of nuclear factor κB ligand (RANKL)/osteoprotegerin (OPG), IL-17, and MMP-3 expression in synovial fibroblasts from rheumatoid arthritis (RASFs) patients." (PMID 26273599, 2015). "Epidemiological studies have investigated the association between matrix metalloproteinase-3(MMP-3) gene-1171 5A/6A polymorphism and rheumatoid arthritis (RA), but the results were inconsistent." (PMID 25403368, 2014). "Matrix metalloproteinase-3 (MMP-3) is involved in the immunopathogenesis of rheumatoid arthritis (RA), but little is known about its relationship to genetic susceptibility and biomarkers of disease activity, especially acute phase reactants in early RA." (PMID 23690656, 2013). "Of note, MMP-1 and MMP-3 have been known for their involvement in tissue destruction in rheumatoid arthritis and their expression in synovial fibroblast have been associated with the invasive ability of these cells." (PMID 21961038, 2011). "This is in line with previous reports that demonstrated elevated MMP-3 expression levels in synovial fluids and sera of patients with rheumatoid arthritis as well as expression in joints of CIA rats." (PMID 20731827, 2010). "The inhibitory effect on MMP-3 levels, however, has been reported in chondrocytes and in the serum level in rheumatoid arthritis patients after intra-articular injection of glucocorticoids." (PMID 19906289, 2009). "However, previous studies have reported that MMP-3 levels were normal in FM and significantly lower than in rheumatoid arthritis and spondyloarthritis, suggesting that it is unlikely to be a useful biomarker for the symptoms in FM." (PMID 39838480, 2025). "Stromelysin-1 (MMP-3) is known to degrade components of the extracellular matrix, including proteoglycans, gelatin, fibronectin, laminin, and various types of collagens found in increased amounts in the sera of patients with longstanding rheumatoid arthritis." (PMID 39064453, 2024). "In addition, hAlb-CTLA4Ig was also cleaved by MMP3, an inflammatory enzyme highly expressed in rheumatoid arthritis." (PMID 36797799, 2023). "Besides, CD4+ IL-21+ cells sorted from the synovial fluid can induce fibroblast-like synovial cells to secrete MMP-1 and MMP-3, which promote inflammation and joint pathological changes in patients with rheumatoid arthritis." (PMID 37628716, 2023). "Increased serum levels of MMP3 have been observed in rheumatoid arthritis (RA) as well as OA." (PMID 35329213, 2022). "Besides, RSV is also known to reduce TNF-α-induced IL-1β and MMP-3 production by suppressing PI3K-Akt signaling in fibroblastoid synoviocytes of rheumatoid arthritis." (PMID 34497510, 2021). "This may be an indication that MMP-3 may warrant further investigation as a biomarker in differentiating rheumatoid arthritis and other forms of arthritis." (PMID 33211763, 2020).
rheumatoid arthritis (continued). "Similarly, TNFα-induced expression of matrix metalloproteinases (MMP1 and MMP3) in synovial fibroblasts from a rheumatoid arthritis patient was suppressed by P-Dex." (PMID 20836843, 2010). "Moreover, vitamin K2 supplementation reduced serum MMP-3 levels in subjects with rheumatoid arthritis, which may also support the concept of vitamin K as an inhibitor of elastin degradation." (PMID 36835797, 2023). "However, targeting, for example, the RIPK1 pathway with GSK2982772 in rheumatoid arthritis showed decrease production of MMP3 compared with the placebo group and may be a potential avenue for treatment in cGVHD." (PMID 37526081, 2023). "Resveratrol has shown anti-rheumatoid arthritis properties by decreasing rheumatoid arthritis patients’ swelling, tenderness and disease activity via decreasing the biochemical markers of inflammation such as MMP-3, ESR, C-reactive protein, IL-6 and undercarboxylated osteocalcin." (PMID 36551806, 2022). "Therefore, it has been suggested that MMP3 was a biomarker of rheumatoid arthritis, which could reflect the severity of the disease." (PMID 35571618, 2022). "Interleukin-21 (IL-21), produced by stimulated CD4+ T immune cells, plays a significant role in the progression of rheumatoid arthritis (RA) via induction of inflammatory factors and matrix metalloproteinases (MMPs) such as MMP-3 and MMP-13." (PMID 32380783, 2020). "Matrix metalloproteinase-3 (MMP-3) plays an important role in the pathology of rheumatoid arthritis (RA) and ankylosing spondylitis (AS)." (PMID 24641725, 2014). "In patients with OA, the immunoexpression levels of TNF-α, IL-1β, IL-7, MMP-1, MMP-2, and MMP-3 were significantly higher in patients with active rheumatoid arthritis (RA), whereas the immunoexpression levels of IL-1, IL-2, IL-4, IL-6, IL-15, IL-18, and MMP-3 were not statistically different." (PMID 40004793, 2025). "A notable aspect of this study was the impact of AG on MMPs, including MMP-1, MMP-3, MMP-8, and MMP-13, which are key targets in inflammatory arthritis, including OA and rheumatoid arthritis." (PMID 39125316, 2024). "Previous studies have shown that the genetic knockdown of MAFB in chondrocytes using siRNA (MAFB Si chondrocytes) abrogated the increased matrix metalloproteinase (MMP3 and MMP13) gene expression in rheumatoid arthritis." (PMID 39054551, 2024). "Furthermore, XIST is involved in the pathogenesis of SLE and rheumatoid arthritis (RA) and can promote the expression of MMP3 and caspase-3, which are important molecules contributing to KD." (PMID 36829193, 2023). "In vitro experiments have shown that the JBQG drug serum can inhibit the expression of cytokines (IL-6, IL-8, IL-22, IL-23), chemokine proteins and mRNA expression (MMP-1, MMP-2, MMP-3, MMP-9, MMP-13) in rheumatoid arthritis synovial fibroblasts (RA-FLS)." (PMID 37180723, 2023). "In joint inflammatory disease, synoviocytes expressed MMP1, MMP3, and MMP10 to increase their invasiveness to destruct the cartilage in rheumatoid arthritis." (PMID 37006258, 2023). "FSTL1 induced MMP3 and MMP13 gene expression in rheumatoid arthritis synoviocytes requiring MAPK, JAK/STAT3 and NF-κB pathways." (PMID 36497076, 2022). "Elevated serum MMP-3 levels have previously been reported in connective tissue disease: systemic lupus erythematosus (SLE) and rheumatoid arthritis (RA) and also in myasthenia gravis." (PMID 35529854, 2022). "Our findings showed that MMP3 positively regulated NSCLC, especially LUSC by participating in transcriptional misregulation in cancer, the IL-17 signaling pathway, and the rheumatoid arthritis pathway." (PMID 35227278, 2022). "SLC7A5, as an amino acid transporter, participates in cell invasion and regulates the protein levels of MMP3 and MMP13 through mTOR signaling in rheumatoid arthritis fibroblast-like synovial cells." (PMID 35785145, 2022). "MMP3, a member of the MMP family, has been reported to be highly expressed in OA and rheumatoid arthritis." (PMID 34124036, 2021).
rheumatoid arthritis (continued). "In rheumatoid arthritis, CYR61 was found to be overexpressed in the synovial tissue of patients and was able to induce the expression of IL-6, CCL20, IL-1β, and MMP-3 in cultured fibroblast-like synoviocytes from patients." (PMID 33542676, 2021). "Downregulation of PTGS2 reduces the expression of IL-6 and MMP-3, and the downregulation of MMP-3 and PTGS2 have been shown to help inhibit synovial fibroblast proliferation and joint inflammation in rheumatoid arthritis." (PMID 34917160, 2021). "Since the expression of matrix metalloproteinase-3 (MMP-3) is enhanced in rheumatoid arthritis (RA), AHA production could also be increased." (PMID 32586370, 2020). "We examined leptin and adiponectin concentrations and inflammatory markers such as metalloproteinase-3 (MMP-3) in 136 patients with rheumatoid arthritis (RA) (26 males and 110 females, 69.6 ± 9.3 years) and 78 controls (36 males and 42 females, 66.7 ± 15.0 years)." (PMID 32985609, 2020). "Curcumin, another inhibitor of mTOR signaling, was also reported to alleviate rheumatoid arthritis-induced inflammation and synovial hyperplasia by reducing inflammatory mediators like IL-1β, TNF-α, MMP-1, and MMP-3." (PMID 32867828, 2020). "HIF-1α acts as a key regulator during inflammation, increasing pro-inflammatory cytokines (e.g., TNF-α, IL-1β, IL-6, and IL-8), matrix metalloproteinases (e.g., MMP-1, MMP-3, and MMP-9), and pathways of glucose metabolism in rheumatoid arthritis (RA)." (PMID 33374961, 2020). "In the bootstrap resampling, we selected several important rheumatoid arthritis genes such as MMP genes (MMP1, MMP3), CCL genes (CCL3, CCL4, and CCL26), and IL genes (IL6, IL8, IL19, and IL24)." (PMID 31371761, 2019). "In the hypoxia microenvironment of rheumatoid arthritis tissue, monocytes secreted several inflammatory factors, such as IL-6, TNF-α, IL-1β and MMP-3, which contributed to the joint inflammation in RA." (PMID 29456830, 2018). "This is consistent with data in rheumatoid arthritis, where TH‐17 cells induced MMP‐1 and MMP‐3 production." (PMID 29210073, 2018). "Specifically, TAK1 expression has been observed in the synovial tissues of OA and rheumatoid arthritis (RA) patients, and TAK1 knockdown in rheumatoid arthritis-affected synoviocytes reduced matrix metalloproteinase-3 (MMP-3) expression by IL-1β." (PMID 28668088, 2017). "In rheumatoid arthritis (RA), C-reactive protein (CRP), and matrix metalloproteinase-3 (MMP-3) are widely used as serologic biomarkers, but they lack sufficient specificity or precision." (PMID 27209430, 2016). "Immunohistochemical staining of rheumatoid nodules has shown positive staining of epithelioid cells for HLA-DR, CD68, lysozyme, MMP-2, MMP-3, MMP-9 and Ki67." (PMID 19604347, 2009). "Kaempferol reduced the production of matrix metalloproteinases-1 (MMP-1), matrix metalloproteinases-3(MMP-3), COX-2, and prostaglandin E2 (PGE2) in response to interleukin-1β (IL-1β) as well as the proliferation of both unstimulated and IL-1β-stimulated rheumatoid arthritis synovial fibroblasts." (PMID 38496846, 2024). "Additionally, the KEGG pathway analysis showed 14 pathways (p < 0.05) related to potential targets, and CCL5, MMP3 and MMP1 were enriched in the rheumatoid arthritis pathway." (PMID 36615560, 2023). "Similar effects of CBD under inflammatory conditions connected with rheumatoid arthritis development are observed in synovial fibroblasts, where CBD decreases MMP-3 level by activating transient receptor potential ankyrin (TRPA1), and increasing intracellular calcium levels." (PMID 34691360, 2021). "MMP3 is involved in the IL-17 signaling pathway, TNF signaling pathway, and rheumatoid arthritis." (PMID 34830910, 2021). "Swollen 28-joint count (SJC-28), Tender 28-joint count (TJC-28), CRP, erythrocyte sedimentation rate (ESR), uncarboxylated osteocalcin (UCOC), MMP-3, TNF, IL-6, and DAS28-ESR (Diseases Activities Score-28 for Rheumatoid Arthritis with ESR) levels are also decreased." (PMID 34770980, 2021).